Y_RNA (Y RNA )
Gene: Miscellaneous RNA gene on chromosome 12 (7,784,403 to 7,784,511, reverse strand). Ensembl gene ENSG00000201549.
Homologues: Paralogues in human: Y_RNA (78% identical), Y_RNA (77% identical), Y_RNA (76% identical), RNY1P5 (75% identical), Y_RNA (75% identical), Y_RNA (74% identical), Y_RNA (73% identical), Y_RNA (72% identical), RNY1 (72% identical), RNY1P1 (72% identical), RNY1P6 (72% identical), Y_RNA (71% identical), and 89 more.